TERT (telomerase reverse transcriptase)
Diseases named in the same sentence as TERT in open-access papers (continued):
Sharing a sentence is not in itself a finding about the gene and the disease.
lung adenocarcinoma (continued). "We examined TERT mRNA expression in surgical specimens from 22 lung adenocarcinoma patients according to Kras status using quantitative RT-PCR assay." (PMID 27329725, 2017). "Quantitative RT–PCR analysis revealed that TERT expression was significantly higher in Krasmut lung adenocarcinomas than in Kraswt lung adenocarcinomas." (PMID 27329725, 2017). "A mutual exclusive relationship between KLF4 and TERT expression levels was revealed in Lung Adenocarcinoma (TCGA, Nature 2014, 230 patients/230 samples)." (PMID 27153563, 2016). "Further analysis found that CNV of TERT was correlated with progression free survival of lung adenocarcinoma." (PMID 26497366, 2015). "A recently published whole genome study directly supports our finding by demonstrating amplification of TERT in lung adenocarcinoma." (PMID 26497366, 2015). "In addition, TERT mRNA expression was increased in 20 tumor types including lung adenocarcinomas (LUAD) and lung squamous cell carcinomas (LUSC) (data from The Cancer Genome Atlas (TCGA))." (PMID 37085672, 2023). "As Kras mutations have been associated with cigarette smoking in lung adenocarcinomas, the TERT expression between smokers and nonsmokers was analyzed." (PMID 27329725, 2017). "We found that Kras mutations increased TERT (telomerase reverse transcriptase) mRNA expression and telomerase activity and telomere length in both immortalized bronchial epithelial cells (BEAS-2B) and lung adenocarcinoma cells (Calu-3)." (PMID 27329725, 2017). "Four loci, 5p15.33 (TERT), 6p21.3 (BTNL2), 3q28 (TP63) and 17q24.2 (BPTF), previously shown to be strongly associated with overall lung adenocarcinoma risk in East Asians, were re-discovered as loci associated with a higher susceptibility to EGFR mutation-positive lung adenocarcinoma." (PMID 27501781, 2016). "Also, the CNVs of PBXIP1 and TERT presented significant upregulation of corresponding gene expressions and were found to be independently predictive of lung adenocarcinoma patient survival." (PMID 26497366, 2015). "In addition, the combined effect of the CNVs of PBXIP1 and TERT on lung adenocarcinoma prognosis was assessed." (PMID 26497366, 2015). "There is biologic plausibility for this finding because mean relative telomere length has been associated with four genetic variants of the hTERT gene, including rs2736100, and TERT gene amplification is responsible for TERT mRNA overexpression in a majority of lung adenocarcinomas." (PMID 23870182, 2013). "TERT siRNA may, therefore, be a strong candidate for highly selective therapy for chemoprevention and treatment of lung adenocarcinoma." (PMID 23677713, 2013). "We report conclusive evidence that common genetic variants in the TERT-CLPTM1L locus on chromosome 5p15.33 are associated with risk for lung adenocarcinoma in non-smoking Asian women." (PMID 20700438, 2010). "In this study of lung adenocarcinoma in East Asian never-smoking women, we report a highly significant association with the common SNP, rs2736100, which localizes to the TERT-CLPTM1L locus on chromosome 5p15.33." (PMID 20700438, 2010). "Amplifications in 5p15.33 (TERT) and 7q31.2 (MET) have been previously found to characterize lung adenocarcinoma (LUAD) profiles." (PMID 40843133, 2025). "By integrating the copy number information, we identified that four of above defined 129 upregulated eRNAs targeting FOXO6, TERT and PAX9 were activated by CNA in lung adenocarcinoma samples." (PMID 33042282, 2020). "Unexpectedly, rs2853677 is associated only with lung adenocarcinoma and is not related to SCLC, although SCLC expresses similar levels of Snail1 compared with lung adenocarcinoma and SCLC expresses more TERT than lung adenocarcinoma." (PMID 27191258, 2016). "We accessed The Cancer Genome Atlas (TCGA) public database to analyze any correlation among Snail1, TERT and E-cadherin (an important cell-cell adherent junction protein whose downregulation is a golden mark of the EMT) in lung adenocarcinoma." (PMID 27191258, 2016).
lung adenocarcinoma (continued). "Additionally, it is perfectly correlated with a nonsynonomous variant in TERT (rs61748181, A279T) that was recently reported as a novel lung adenocarcinoma risk locus by deep sequencing and direct genotyping of 5,164 cases and 5,716 controls of European ancestry." (PMID 27579533, 2016). "Gene variations rs2736100 and rs2853676 in TERT and rs401681 and rs31489 in CLPTM1L had significant direct associations on lung adenocarcinoma without indirect effects through nicotine dependence." (PMID 25233467, 2014). "We found that smokers had higher TERT levels than non-smokers in lung adenocarcinoma patients." (PMID 27329725, 2017). "Furthermore, a prognostic significance for the CNVs of TERT and PBXIP1 in lung adenocarcinoma was found, which may lead to translation into the clinic and improve outcomes for patients with this fatal disease." (PMID 26497366, 2015). "Our results may also indicate that there is common and frequent chromosome abnormality in lung adenocarcinomas independent of ALK fusion, such as the 5p15.33 region, including TERT." (PMID 23289484, 2013).
thyroid tumor (44 papers, 2014 to 2025). A benign or malignant neoplasm affecting the thyroid gland. "Additional studies are thus urged to clarify the function and mechanism of TERT co-mutation events in the malignant progression of thyroid tumors." (PMID 39235852, 2024). "In one study, a group of thyroid tumors was examined for TERT promoter mutations preoperatively on fine needle aspiration cytology material and TERT mutations were only found in malignant tumors, illustrating its diagnostic potential." (PMID 39363120, 2024). "These contradicting findings are also of great interest for thyroid tumors, as the status of TERT promoter mutations together with BRAF mutations have been shown to be associated with clinicopathological aggressiveness." (PMID 37418389, 2023). "We report for the first time three BRAF non-V600E variants previously undetected in thyroid tumors, including one concomitant with TERT mutation and associated with distant metastasis." (PMID 36835466, 2023). "TERT promoter mutations have been recognized as potent prognosticators of adverse outcomes in thyroid neoplasms." (PMID 37746968, 2023). "The clinicopathological characteristics of the TERT promoter mutations in brain and thyroid tumors have been previously reported by researchers at our institute." (PMID 35135543, 2022). "The majority of the 10 thyroid tumours with established TERT promoter mutations and TERT mRNA expression demonstrated nuclear, dot-like TERT ISH signals in subsets of tumour cells (TERT1; n=6/10; 60%, TERT2; n=7/10; 70%)." (PMID 34011619, 2021). "Sanger sequencing using DNA from the thyroid tumor showed an indel mutation, c.1-132_1-124delinsT, composed of a deletion (c.1-132_1-125del) as well as a hotspot mutation (c.1-124C>T(C228T)) in the TERT promoter." (PMID 33375021, 2020). "Focusing only on thyroid tumours with TERT promoter mutations and liver tumours with CTNNB1 mutations, we compared the proportions of polyclonal vs. monoclonal tumours between the sexes." (PMID 32859912, 2020). "In order to continue disclosing and understanding TERTp mutations and TERT mRNA expression role in thyroid tumours, a series of frozen thyroid tumours was evaluated." (PMID 32659948, 2020). "Telomerase re-activation and TERT genetic alterations, such as the TERTp mutations have been reported in thyroid tumours." (PMID 32659948, 2020). "Currently, mutations in TERT promoter are among the more common genetic abnormalities observed in cancers and the most frequent alterations observed in aggressive thyroid tumors." (PMID 31200515, 2019). "We examined the utility of microfluidic digital PCR (dPCR) for detection of BRAF and TERT mutations in thyroid tumors." (PMID 31810221, 2019). "In other 5 studies, whose data about tumor size was unqualified, TERT promoter mutations were also found to have high prevalence in larger thyroid tumors (P < .01 in all 5 studies, respectively)." (PMID 30024548, 2018). "However, RAS-mutant thyroid tumors typically exhibit a more indolent clinical course compared to those harboring BRAF V600E or TERT mutations." (PMID 40940948, 2025). "TERT promoter mutations are molecular events frequently associated with high-risk thyroid tumors with poor outcomes and may identify cases at risk of dissemination." (PMID 39363120, 2024). "Usually, TERT promoter mutations are restricted to larger thyroid tumors in older patients." (PMID 39363120, 2024). "Thus, BRAF non-V600E mutated tumors should be thoroughly investigated, looking for thyroid tumor progression-related molecular changes such as TERT promoter mutation." (PMID 36835466, 2023). "The same is true for other emerging technologies that also show higher sensitivity than Sanger Sequencing, such as next generation sequencing (NGS), that have been used to identify genetic alteration in genes other than TERT and that have been associated with aggressive thyroid tumors subtype." (PMID 33776938, 2021).
thyroid tumor (continued). "The finding of both a codon 600 BRAF and a C228T TERT promoter mutation in the TCV-PTC arising ectopically in our case mirrors previous observations in high-risk cases of thyroid tumors arising within the thyroid gland, as our patient developed distant metastases 4 years after surgical removal." (PMID 33466206, 2021). "The presence of TERT promoter mutations in synergy with BRAF mutations has been associated with aggressive thyroid tumor characteristics, which include lymph node metastasis, distant metastasis, tumor recurrence, multifocality, extrathyroidal extension, and patient mortality." (PMID 32751138, 2020). "Besides BRAFV600E, TERT promoter mutations have also been observed to coexist with RAS mutations in aggressive thyroid tumors; however, the clinical significance of this oncogenic duet is still not fully understood." (PMID 32751138, 2020). "Literature reports the use of TERT promoter mutation screening programs in thyroid tumors in order to select patients who would benefit from adjuvant treatment and closer follow-up, since many studies related the presence of these mutations with poor prognosis." (PMID 32850388, 2020). "Second, we examined TERT mutations in patients with thyroid tumors." (PMID 31810221, 2019). "In addition to somatic mutations, we found several single‐nucleotide polymorphisms (SNP) in analyzed TERT promoter region in different thyroid tumor types." (PMID 31408918, 2019). "We also analyzed TERT promoter mutations, a recent molecular change associated to thyroid tumors." (PMID 25988151, 2014). "The finding that the aggressiveness of a thyroid tumor with a TERT promoter mutation may be dependent on the presence of concurrent mutations is an important concept for thyroid specialists to consider when counseling patients regarding risk stratification, management, and extent of surgery." (PMID 36672362, 2023). "Therefore, we hypothesized that in thyroid tumours, telomere shortening upon proliferative pressure leads to a configuration change at TERT that facilitates the occurrence of pathogenic events." (PMID 35979662, 2022). "In an experimental trial in mice, the TERT mutant promoter not only produced poorly differentiated thyroid tumours, but also overactivated cytokines and chemokines signalling pathways, which is not normally seen in those tumours lacking the TERT mutant." (PMID 41305531, 2025). "The PTCs with DMs can be considered the first stage in thyroid tumor progression and dedifferentiation from which an accumulation of TERT activating events is prone to occur." (PMID 40272676, 2025). "When the TERT promoter mutation coexists with BRAFV600E, the thyroid tumor tends to behave more aggressively." (PMID 39235852, 2024). "Overall, these analyses narrowed the list of candidate ETS factors regulating TERT transcription in thyroid tumors down to 20 members." (PMID 35053525, 2022). "Our results point to a greater complexity of TPM-mediated regulation of TERT transcription from what was previously reported and caution against adopting what has been demonstrated in other cancer types carrying TPMs into thyroid tumors." (PMID 35053525, 2022). "Mutations in the promoter region of the telomerase reverse transcriptase (TERT) gene are enriched in patients with advanced thyroid tumors." (PMID 35053525, 2022). "Copy number analysis reinforced this observation, as five of the six thyroid tumours with copy number gains at TERT locus were anaplastic thyroid tumours or differentiated with an undifferentiated component." (PMID 35979662, 2022).
thyroid tumor (continued). "This was true for the thyroid tumours as well as for the HeLa cells used as controls, suggesting a true biological role for nuclear TERT mRNA." (PMID 34011619, 2021). "In thyroid fine-needle aspiration cytology materials the authors reported that 35% of the benign lesions were TERT positive, TERT sensitivity being increased in management of suspicious thyroid tumours when concomitant lymphocytic thyroiditis were excluded." (PMID 32659948, 2020). "The primary thyroid tumor, pancreatic metastasis, and cervical lymph node metastasis were both positive for BRAF V600E and TERT promoter (C288T) mutations." (PMID 31781034, 2019). "Among the thyroid tumors with increased TERT gene copy numbers, 2/4 HCC samples and 1/2 PDTC/ATC samples were positive for c.‐124C > T mutation." (PMID 31408918, 2019). "In another study, a 6.0-cm thyroid tumor, which met the initial criteria for NIFTP, had concurrent RAS and TERT promoter mutations." (PMID 30428594, 2018). "Thus, our results underscore the need to consider TERT promoter methylation in screening tools for the stratification of thyroid tumours according to their malignant potential and to report TERT gene expression results along with tumour cellular composition." (PMID 35979662, 2022). "Similarly, studies aimed at the analysis of TERT promoter methylation also point to methylation as a recurrent event in clinically aggressive thyroid tumours." (PMID 35979662, 2022). "Nevertheless, distinguishing which ETS (and other) factors are important in the reactivation of TERT in aggressive thyroid tumors is a necessary first step towards enabling new methods of blocking TERT expression and ultimately inhibiting cell growth in a cancer-specific manner." (PMID 35053525, 2022). "Pediatric thyroid tumors, which are considered not so aggressive, have been found to be negative for the presence of TERT promoter mutations." (PMID 33572167, 2021). "We analysed frozen samples from a series of benign and malignant thyroid tumours, displaying non-aggressive features and low mutational burden in order to evaluate the presence of TERTp mutations and TERT mRNA expression in these settings." (PMID 32659948, 2020). "Even in the absence of the TERTp mutations, benign and malignant thyroid tumours had TERT mRNA expression." (PMID 32659948, 2020). "In a recent study, some thyroid tumor showed increased TERT mRNA expression even in the absence of TERT promoter mutations, which have a significantly high recurrence rate." (PMID 33374707, 2020). "Our analysis identified nine thyroid tumor samples with increased TERT locus copy number." (PMID 31408918, 2019). "Notably, TERT promoter mutation is not the only mechanism through which thyroid tumors achieve TERT activation, with promoter hypermethylation and copy number gains representing alternative mechanisms." (PMID 40396891, 2025). "TERT promoter mutations have been found to be associated with the presence of the BRAF-V600E mutations: the coexistence of BRAF-V600E and TERT mutation has been demonstrated to define a particularly aggressive group of thyroid tumors and in particular with tumor recurrence and mortality." (PMID 33572167, 2021). "Even though the series is small, it is possible to report that malignant thyroid tumours are frequently TERT mRNA positive in the absence of hotspot TERTp mutations and the mechanism by which TERT re-expression occurs in these cases remains largely unknown." (PMID 32659948, 2020). "In addition, 5% of thyroid tumors were found to have ≥3 copies of TERT." (PMID 31408918, 2019). "We also tested the role of BRAF V600E and TERT in thyroid tumor growth using the BRAF V600E inhibitor PLX4032 and stable TERT knockdown to suppress the MAPK pathway and the TERT, respectively, in K1 cell, from which xenograft tumors were derived." (PMID 29422527, 2018). "Our work points to an intricate, still not fully characterized, regulatory network of TERT transcription in thyroid tumors." (PMID 35053525, 2022).